CASP8 (caspase 8)
Diseases named in the same sentence as CASP8 in open-access papers (continued):
Sharing a sentence is not in itself a finding about the gene and the disease.
cancer (continued). "This is because caspase activation, such as that of caspase-8, is required for apoptotic cell death, but necroptosis can eliminate cancer cells when caspase-8 is silenced, inhibited, or mutated." (PMID 28025559, 2016). "Somatic deletions and point mutations of CASP8 have been observed in several cancer types including colorectal, head and neck, gastric cancer and neuroblastoma." (PMID 26740556, 2016). "The majority of investigators observed an association of the CASP8 -652 6N Del or the CASP8 Asp302His variant with reduced cancer susceptibility." (PMID 27507139, 2016). "Mutation frequency in FAT1, NOTCH1 and CASP8 in HNSCC is significantly higher (p < 0.05) in comparison to other cohorts of squamous or similar cancers." (PMID 26506389, 2015). "DOX is a potent DNA damaging drug and induces apoptosis in cancer cells via two distinct pathways: membrane associated death receptor pathway by activating caspase-8 and the mitochondrial pathway by activating caspase-940." (PMID 26149967, 2015). "CASP8 has been implicated in several cancer types both through germline variants and somatic mutations." (PMID 25855136, 2015). "A six-nucleotide insertion-deletion polymorphism in the CASP8 promoter has been associated with susceptibility to multiple cancers with the deletion variant having reduced caspase-8 activity and conferring decreased risk of cancer." (PMID 25615575, 2015). "Owing to the fundamental physiological function of CASP8 in apoptosis, it is associated with numerous human diseases, especially cancers." (PMID 24819879, 2014). "The common −652 6N del variant in the CASP8 promoter (rs3834129) has been described as a putative low-penetrance risk factor for different cancer types." (PMID 24465592, 2014). "Caspase-8 has been reported to be silenced in a subset of human cancers owing to gene deletion, mutation or promoter hypermethylation, all resulting in a reduced capacity to trigger apoptosis [reviewed in 40]." (PMID 24931006, 2014). "Caspase 8 (CASP8) plays a critical role in the apoptotic pathway and aberrant regulation of this pathway causes many diseases including cancers." (PMID 23844036, 2013). "The indel polymorphism, rs3834129 (CTTACT/−, written as 6 bp/del in the following text), in the promoter region of the CASP8 gene was reported to be associated with susceptibility to a wide range of cancers including CRC in Chinese populations." (PMID 23844036, 2013). "In conclusion, findings of this study have shown a common insertion-deletion variation in the promoter region of the CASP-8 gene as a low penetrance susceptibility locus for certain common types of human cancers." (PMID 23170140, 2012). "In our study, we examined the association of the −652 6N ins/del polymorphism in the CASP-8 gene with the risk for cancer by meta-analysis." (PMID 23170140, 2012). "The CASP-8 −652 6N ins/del (rs3834129) polymorphism has been previously reported to influence the progression to several cancers." (PMID 23170140, 2012). "A negative association was observed between the del allele, del allele carrier and ins/del genotype of the −652 6N ins/del polymorphism in CASP-8 gene and cancer risk." (PMID 23170140, 2012). "Findings of previous studies showed that some variants in CASP-8 gene are associated with susceptibility to various human cancers." (PMID 23170140, 2012). "In this human genome epidemiology (HuGE) review and meta-analysis, the aim was to identify the association between CASP-8 −652 6N ins/del polymorphism and cancer risk." (PMID 23170140, 2012).
cancer (continued). "Accumulating studies have reported that two common single nucleotide polymorphisms (SNPs) in the CASP8 promoter gene, -652 6N ins/del (rs3834129) and D302H (rs1045485), were associated with risk of cancers." (PMID 23554680, 2011). "Data from our study also demonstrated that treatment with 5-FU caused a significant increase in unmethylated CASP8 and in CASP8 mRNA in all 3 cancer lines." (PMID 20132554, 2010). "We found that increased expression of cytoplasmic caspase-8 and bcl-2 protein was strongly associated with low Fuhrman's grade of carcinomas (p = 0.019 and p = 0.041, respectively)." (PMID 19222834, 2009). "It has been asserted that this specific variant has direct functional effects on cancer risk on the basis that the deletion destroys a stimulatory protein 1 binding site and decreases CASP8 transcription." (PMID 18362937, 2008). "We also observed a significant CASP8 sQTL in melanocyte and other GTEx eQTL datasets relevant to cancers with associations for this locus (marked by rs10804111; r2 to rs10931936 = 0.62; D’ = 1) reflecting alternative splicing events at the exon 8 to exon 9 junction." (PMID 41542517, 2026). "Furthermore, the analysis of cancer databases showed that the mutations at these two residues are quite common for caspase-8 in several human cancers." (PMID 38730267, 2024). "Although defects in the epidermal barrier, mutations in Casp8 and individual components of the immune system have previously been associated with cancer, our model links defective epidermal barrier to autophagy activation and cancer susceptibility." (PMID 39625985, 2024). "However, aspirin and LR-AFY06 treatment significantly improved caspase-8 mRNA downregulation caused by carcinoma in the mice." (PMID 38572238, 2024). "Indeed, upon Src constitutive activation or EGF-mediated activation, Caspase-8 is associated with the cellular membrane, allowing sustained migration in cancer cells." (PMID 37444381, 2023). "Earlier and recent studies have showed that a high ratio of Bax to Bcl-2, activation of caspase family, including caspase-3, caspase-8 and caspase-9, as well as the loss of mitochondrial transmenbrane potiential are observed in monensin-induced apoptosis of several human cancer cell lines." (PMID 36896461, 2023). "It has been reported that the susceptibility to necroptosis by several human cancers could be explained by the tendency to genetically disrupt Caspase-8 activation." (PMID 37628814, 2023). "Certainly, a loss of Caspase-8 expression or function in cancer cells may support evasion from apoptosis and therefore promote cancer progression and resistance to radio and chemotherapy." (PMID 37444381, 2023). "The loss of CASP8 sensitizes cancer cells to necroptosis via a complex regulatory mechanism." (PMID 35562533, 2022). "Moreover, we observed phase-shifted transcript pairs related to cancer hallmark genes like CASP8 and Mitogen Activated Protein Kinase 3 (MAPK3) that were unique to HCT116_NR1D1KO." (PMID 35552415, 2022). "Consequently, upon TNF-induced caspase-8 activation, caspase-8 cleaved GSDMC at 362 LELD 365 to release a pore-forming N-terminal domain causing cancer cell pyroptosis." (PMID 35608339, 2022). "Likewise, polymorphism rs3834129 in CASP8 gene has been broadly studied regarding cancer, particularly cancer development." (PMID 35678683, 2022). "It remains speculative whether increased expressions of CASP3, CASP6, and CASP8 may be associated with enhanced pyroptosis and cell death, thereby reducing the cancer’s aggressiveness." (PMID 35928267, 2022). "Past pan-cancer analyses also show that cells with CASP8 mutations escape immune surveillance." (PMID 35437329, 2022). "Cancers with low caspase-8 expression or mutations, which block its pro-apoptotic activity, may not respond to the standard treatments, which usually rely on apoptosis induction." (PMID 33026575, 2021).
cancer (continued). "Low expression of caspase-8 or mutations that block its pro-apoptotic activity may be associated with apoptosis resistance and thereby contribute to cancer metastasis." (PMID 33810241, 2021). "The inactivating mutation of caspase-8 is surprisingly infrequent among various human cancers." (PMID 34367939, 2021). "It has also been confirmed that disturbances in CASP8 expression may be associated with the development of resistance to anti-cancer therapy." (PMID 33800294, 2021). "This may explain why some cancer types promote the expression of mutated caspase-8 and why they even benefit from TRAIL-R expression." (PMID 33026575, 2021). "Interestingly, CASP8 showed similarly increased mutation rate both in early- and late-stage cancers with TMD, while HRAS mutations appeared linked with TMD only in late-stage tumors – pointing toward a timing specificity of TMD-linked evolutionary pressures." (PMID 34307377, 2021). "While much has been learned about the diverse functions of wild-type caspase-8, primarily via gene knockout studies, the functional properties and phenotypic effects of cancer-associated caspase-8 mutations are largely unknown." (PMID 34362880, 2021). "In addition, the prevalence of caspase-8 mutations was substantially higher in carcinomas (p-value = 0.05) and there was significant reduction of the apoptotic activity in tumors harboring the caspase-8 mutations." (PMID 34836311, 2021). "However, one single nucleotide polymorphism SNP on the CASP-8 promoter (−652 6 bp ins/del) is reported to negatively co-relate with cancer progression." (PMID 35047986, 2020). "Inhibition or mutation of CASP8 predisposes a wide variety of cancers to necroptosis." (PMID 33108350, 2020). "Thus, the tendency of human cancers to genetically disrupt caspase-8 can amply explain their relative susceptibility toward necroptosis." (PMID 32752206, 2020). "Besides the involvement of CASP8 -652 InsDel and CASP8 Asp302His in cancer susceptibility, recent studies investigated the possible impact of both polymorphisms on the outcome of patients with existing cancer." (PMID 31467295, 2019). "Our studies show that CASP8-mutated carcinomas display a shared immune signature." (PMID 30775178, 2019). "The central role of Caspase-8 in apoptosis suggests that its loss of expression or the impairment of its apoptotic activation may trigger cancer cell resistance to therapeutic approaches that relay on the apoptotic cascade." (PMID 30501030, 2018). "Various cancer types loose expression of Ripk3 and/or acquire Caspase-8-inactivating mutations." (PMID 29867129, 2018). "Our results highlight the role of the CASP8 -652 6N ins/del polymorphism in decreasing cancer risk." (PMID 28915630, 2017). "Similarly, the CASP8 -652 6N ins/del polymorphism was associated with decreased cancer risk in both the high quality (DD vs. II: OR=0.67, 95% CI=0.58–0.77) and low quality study groups (DD vs. II: OR=0.87, 95% CI=0.77–0.99)." (PMID 28915630, 2017). "Thus, under these experimental conditions, both monovalent and bivalent IAP antagonist treatment resulted in sufficient cIAP1 loss to support RIPK1:caspase-8 complex formation and induction of apoptosis in sensitive cancer cell lines." (PMID 28149532, 2017). "Caspase-8 (CASP8) plays a central role in the apoptotic pathway and aberrant regulation of this pathway may cause cancers." (PMID 24498403, 2014). "In addition, a negative association was found between the del allele of −652 6N ins/del in the CASP-8 gene and cancer risk in the Asian population (OR=0.89, 95% CI=0.83–0.97, P=0.005)." (PMID 23170140, 2012). "The del allele, del allele carrier and ins/del genotype of the −652 6N ins/del polymorphism in CASP-8 gene may serve as protective factors for cancer risk." (PMID 23170140, 2012). "In conclusion, this meta-analysis suggests that the del allele, del allele carrier and ins/del geno-type of the −652 6N ins/del polymorphism in the CASP-8 gene may be protective factors for cancer risk." (PMID 23170140, 2012).
cancer (continued). "In addition, a negative association was also found between the del allele of −652 6N ins/del in CASP-8 gene and cancer risk in the Asian population." (PMID 23170140, 2012). "Caspase-8 is known to activate during death receptor-initiated apoptosis, inducing apoptosis and maintaining immune homeostasis and immune surveillance, while the single genetic variants in CASP-8 and their function in human cancer susceptibility remain to be elucidated." (PMID 23170140, 2012). "The differences may reflect the fact that the association between the CASP8 -652 6N ins/del polymorphism and the decreased cancer risk is more dominant in Chinese populations." (PMID 23554680, 2011). "Polymorphic variation in CASP8 has been reported to influence cancer risk." (PMID 18362937, 2008). "Moreover, biochemical analyses have shown that T lymphocytes with the deletion variant have a reduced caspase-8 activity and activation-induced cell death upon stimulation with cancer cell antigens." (PMID 18362937, 2008). "Notably, a meta-analysis further substantiated the role of CASP8 in cancer susceptibility." (PMID 39351539, 2024). "Indeed, in addition to CASP-8 inactivating mutations that can inhibit its proteolytic activity, Caspase-8 phosphorylation represents another important mechanism to preserve Caspase-8 expression in cancer." (PMID 37444381, 2023). "In addition, several CASP8 gene SNPs are reportedly associated with various types of cancer." (PMID 33995628, 2021). "Our data provide a likely explanation as to why loss of Casp8 and low levels of Ripk1 can be driver mutations in certain types of cancer, leading to chromosome instability that may favor tumor evolution, heterogeneity, acquisition of drug resistance, and heightened risk for tumor relapse." (PMID 30598363, 2019). "Since decreased apoptotic capacity is one of the “hallmarks of cancer”27, one could assume, that the -652Del allele, which generally lowers caspase 8 mediated apoptosis, could be, for the tumor cells themselves, rather a tumor-promoting than a protective factor." (PMID 31467295, 2019). "Finally, this suggests that the del allele, carrier and ins/del genotype of the -652 6N ins/del polymorphism in the CASP8 gene may be protective factors for cancer development." (PMID 29423041, 2018). "Since the development of anoikis resistance is critical for tumour metastasis and loss of caspase-8 in cancers compromises the apoptosis triggered during anoikis, it could be interpreted that caspase-8 pro-migratory effects during metastasis are an indirect consequence of aiding cell survival." (PMID 29854765, 2018). "This variant has been found to decrease CASP8 activity and apoptotic reactivity of T lymphocytes through the cancer cell ex vivo model, and the decreased CASP8 activity may lead to an alteration of normal programmed cell death and result in tumor susceptibility." (PMID 24498403, 2014). "Hence, it is biologically reasonable to hypothesize a potential relationship between the CASP8 −652 6N ins/del polymorphism and cancers." (PMID 24498403, 2014). "It was reported that the CASP8 −652 6N ins/del promoter variant destroy the binding element for stimulatory protein 1 and reduce the expression of CASP8, thus resulting in a reduction in the apoptosis reactivity of T lymphocytes upon stimulation by cancer cells." (PMID 24498403, 2014). "Genetic variation in CASP8 may affect susceptibility to cancer." (PMID 23170140, 2012).
cancer (continued). "Therefore, a human genome epidemiology (HuGE) review and meta-analysis were conducted, including the most recent and relevant articles in order to identify statistical evidence of the association between the CASP-8 −652 6N ins/del polymorphism and cancer risk that have been investigated." (PMID 23170140, 2012). "Therefore, genetic variants in CASP8 may disturb the function of CASP8 and then affect the execution of apoptosis, thus contributing to either the development or progression of human cancers." (PMID 23554680, 2011). "Using genetically engineered mouse models, we find that cancer cell-specific deletion of caspase-8 is sufficient to trigger necroptotic cell death, eliminating most pancreatic precursor lesions." (PMID 42297776, 2026). "Both external validation and IHC analysis consistently confirmed the associations of CBY1, CASP8, PLOD1, and several methylation sites (cg09907170, cg09395195, cg08129017, and cg14808739) with their corresponding cancers." (PMID 42052171, 2026). "In vitro stimulation of CD40tg TRAMP-C1 cancer cells with multimeric CD40L led to a more than 10-fold increase in caspase-8 activity." (PMID 40397730, 2025). "IL-1β treatment resulted in the down regulation of Caspase-8 and -3, thus favoring cancer cell proliferation." (PMID 40725140, 2025). "CD40 triggering on cancer cells activated caspase-8, the initiator caspase of extrinsic apoptosis, assessed by the cell-permeable fluorescent marker FITC-IETD-FMK." (PMID 40397730, 2025). "Caspase-8 catalytic activity in human neutrophils and cancer cell lines can be inhibited by phosphorylation." (PMID 39996713, 2025). "Our research now demonstrates that CD40L on CD8+ T cells halts tumor progression by directly triggering caspase-8 activation in CD40+ cancer cells, resulting in CD40L-mediated cytotoxicity." (PMID 40397730, 2025). "These extracts promote apoptosis in cancer cells by enhancing the activity of caspase-3, caspase-7, caspase-8, and caspase-9." (PMID 40728967, 2025). "The molecular signaling cascades that allow cancer cells to rewire Caspase-8 function and the signaling pathways through which the aberrant expression of Caspase-8 sustains tumor progression, deserve further elucidation." (PMID 41053176, 2025). "The inactivation of genes such as DAPK and Caspase 8, which are crucial for apoptosis, permits cancer cells to avoid programmed cell death, a key feature of cancer's resistance to therapies." (PMID 40959208, 2025). "The association between cancer and increases in CASP3, CASP8, and ATG12/ATG5/ATG16L1 is described in the sections titled “Apoptosis”, “Exocytosis”, and “Autophagy”, respectively." (PMID 41154660, 2025). "Similar consequences of caspase-8 phosphorylation have also been reported in cancer cell lines, primary breast tissue, and lymphocytes." (PMID 39996713, 2025). "In the current study, our results show that IL-1β downregulates the expression of different caspases like caspase-8 and caspase-3, favoring cancer cell survival." (PMID 40725140, 2025). "Overall, this work depicted a novel unexpected role for Caspase-8 in the modulation of cancer cell metabolism, bridging together Src, mTORC1 and NRF2 signaling." (PMID 41053176, 2025). "Caspase 8 (CASP8) is a critical initiator of apoptosis and is dysregulated in various cancers, including ESCC." (PMID 39844051, 2025). "In cancer, silencing of the CASP8 gene in an MDA-MB-231 TNBC cell line reduced cell growth but caused a more aggressive and motile phenotype." (PMID 40806359, 2025). "Of particular interest was the downregulation of caspase 8, a master regulator of PANOptosis, a form of cell death that is highly relevant in cancer." (PMID 40728989, 2025). "CK inhibits AKT1 activity, activates the expression of apoptotic proteases Caspase-3, Caspase-8, and Caspase-9, induces cancer cell apoptosis, and also inhibits cancer cell migration and invasion." (PMID 40422575, 2025).